IL15 (interleukin 15)
Diseases named in the same sentence as IL15 in open-access papers (continued):
Sharing a sentence is not in itself a finding about the gene and the disease.
tumor (continued). "We performed flow cytometric analysis of peripheral blood, splenic cells, and tumor cells from B16F10-bearing C57BL/6 mice and A549-bearing NSI mice with 3 μg/kg murine IL-15 4 weeks after tumor implantation." (PMID 29255466, 2017). "Of note, bortezomib treatment restored IFNγ synthesis and inhibited metastasis in tumor-bearing mice even in the presence of neutralizing antibodies to IL-12 and IL-15." (PMID 28052005, 2017). "Despite these potential advantages for IL-15, IL-2–anti-IL-2 complexes were superior to IL-15–soluble IL-15Rα complexes at supporting the anti-tumor activity of transferred CD8+ T cells." (PMID 29123649, 2017). "IL-15 SA was previously shown to have potent anti-tumor activity in syngeneic murine models of multiple myeloma." (PMID 28574833, 2017). "We also found that the proportion of CD45+ CD122+ cells in tumor-bearing mice was unchanged after IL-15 treatment." (PMID 29255466, 2017). "The aim of this study was to evaluate the potency and mechanism of IL-15 to promote NK cell-mediated killing of PCC and PSC, the latter in order to breach the stromal shield surrounding the tumor rendering the tumor more susceptible for anticancer agents." (PMID 28915646, 2017). "The effect of IL-15 in tumor growth was studied using an orthotopic model in which the anterior prostate lobes of SCID mice were injected with 250,000 22RV1 cells in a collagen-1/PBS suspension." (PMID 28379958, 2017). "We also noted that IFNγ synthesis and control of metastatic growth are both dependent on IL-12 and IL-15 signaling since the blocking of these cytokines decreased IFNγ production and increased the number of tumor pulmonary nodules." (PMID 28052005, 2017). "In this study, we evaluated the role of IL-15 in migration, invasion, proliferation, tumor growth, and angiogenesis using in vitro and in vivo models of PCa." (PMID 28379958, 2017). "Considering the short half-life of exogenous IL-15 in mice, we used the high dose of IL-15 as previous studies described, and we found enhanced tumor growth in the 5 μg IL-15 (200 μg/kg) group." (PMID 29255466, 2017). "Pathological, histological and immunohistochemical analysis of collected tumor tissue was used to study the effect of IL-15 in tumor biology." (PMID 28379958, 2017). "In vivo studies showed that IL-15 increased neutrophil infiltration, and the expression of adiponectin, desmin and alpha smooth muscle actin (α-sma) in the tumor tissue." (PMID 28379958, 2017). "The expression of immunoinhibitory molecules and cytokines, for example, IL-1β, VEGF, IL-10, and TGFβ and downregulation of immunostimulatory cytokines (e.g., IL-2, IL-12, IL-15) allow tumor to escape from immune control." (PMID 28052005, 2017). "Up to this point, the data we have gathered show that in vitro IL-15 decreases motility of PCa in vitro and increases tumor volume, inflammation and neutrophil mobility in vivo." (PMID 28379958, 2017). "Tumors generated in mice treated with IL-15 at 0.0013 ng/mL had increased number of adipocytes infiltrating the tumor cells." (PMID 28379958, 2017). "Our results showed that IL-15 at 0.0013 ng/mL significantly decreased the number of blood vessels in tumor tissue (P<0.05)." (PMID 28379958, 2017). "To determine if IL-15 increased tumor volume by increasing cell proliferation in vivo, we measured the expression of phospho-histone 3 (pH3) by immunohistochemistry." (PMID 28379958, 2017). "An IL-15-based immune therapy apparently reduces tumor cell dissemination, or enhances the elimination of already disseminated (dormant) DTCs, which are probably barely affected by conventional cytotoxic treatments or by irradiation." (PMID 27835865, 2017). "Pmel-1 T cells expanded in IL-15 exhibit enhanced tumor immunity compared with those expanded in IL-2." (PMID 28239463, 2017).
tumor (continued). "Here we show the potent effects of IL-15 SA on immune reconstitution and graft-versus-tumor (GVT)/ graft versus leukemia (GVL) activity in recipients of allogeneic hematopoietic stem cell transplantation (HSCT) in murine models." (PMID 28574833, 2017). "Hu-PB-NK-engrafted NOG-IL-2/IL-15 double Tg mice were further challenged with K562, and the tumor growth was monitored for 3 weeks." (PMID 29222435, 2017). "This is confirmed by functional data indicating an enhanced recruitment of granzyme B+ effector lymphocytes by IL-15 DCs, as compared to IL-4 DCs, and subsequent superior killing of tumor cells by the migrated lymphocytes." (PMID 28099143, 2017). "Neutralization of IL-12 and IL-15 cytokines following intravenous injection of 4T1HA cells increased the number of tumor pulmonary nodules." (PMID 28052005, 2017). "On the other hand, transfecting tumor cells with prototypical IL-15 before injecting them into nude mice did achieve a promising antitumor effect." (PMID 29296227, 2017). "Treatment of tumor-bearing mice with bortezomib further increased the production of these lymphocyte-stimulatory cytokines IL-2, IL-12, and IL-15, which have significant impact on the development of a cytotoxic response mediated by CD8+T cells and NK cells." (PMID 28052005, 2017). "We have previously shown that IL-15 enhances anti-tumor activity in recipients of allogeneic and haploidentical HSCT." (PMID 28574833, 2017). "Adoptively transferred IL-12-, IL-15- or IL-18-activated murine NK cells are shown to display memory features and inhibit tumor growth in IFN-γ and perforin-dependent manner." (PMID 28955340, 2017). "The highest dose administered in human clinical trials is 3 μg/kg, we also treated tumor-bearing mice with 3 μg/kg murine IL-15." (PMID 29255466, 2017). "The capacity of IL-15 designer DC to present tumor-specific antigen was assessed in an HLA-restricted WT1-specific T-cell model." (PMID 28785596, 2017). "In contrast, anti-inflammatory cytokines (IL-2, IL-15, and IL-21) usually activate the antitumor immunity and interfere with tumor development." (PMID 28927416, 2017). "IL-15 signaling was shown to be defective in tumor-bearing mice, which impeded NK cell maturation and IFN-γ production." (PMID 28702032, 2017). "To identify the effect of IL-15 in tumor biology at the genomic level, we performed microarray analysis with RNA extracted from frozen tumor samples." (PMID 28379958, 2017). "Murine IL-15 showed the antitumoral activity in mice with intact immune systems; however, we still observed an increased tumor growth in immunodeficient mice with lower dose of murine IL-15." (PMID 29255466, 2017). "After treatment period, cytokines, Interleukin 2, IL-6, IL-7, IL-10, IL-15, 1 L-17 and TNFα in CT-26 tumor bearing BALB/c mice serum were analysed." (PMID 29246138, 2017). "Not only does IL-1B appear positively correlated with MAP17 in all tumors, other interleukins including IL-15, IL-18, IL-1A, IL-32 and IL-7 and interleukin receptors including IL-10RB, IL-17RC and IL-2RG appear in at least three of the tumor types." (PMID 29228712, 2017). "This study furthers understanding of the mechanisms regulating activation and maintenance of tumor-reactive NK cells and supports the use of IL-15 with adoptive NK cell-based therapies." (PMID 28716068, 2017). "Tumor-derived prostaglandin-E2 suppressed IL-2 cultured NK cells, while IL-15- stimulated cells remain activated." (PMID 28716068, 2017). "Although IL-15 enhanced the trastuzumab mediated tumor defense, an unspecific immune stimulation resulted in preterm animal death due to systemic inflammation." (PMID 27835865, 2017). "Immunostimulatory cytokines (e.g., IL-2, IL-12, IL-15) support lymphocyte differentiation and survival enabling tumor control." (PMID 28052005, 2017).
tumor (continued). "This supports the (micro-array) results, stating that IL-15 DCs are superior in the recruitment of antitumor effector cells as compared to IL-4 DCs, which endorses the suitability of IL-15 DCs as a tumor vaccine." (PMID 28099143, 2017). "Tumor-reactive murine CD8 αβ T cells expanded ex vivo using IL-15 or IL-7/IL-15 mediate increased tumor immunity in vivo as compared to cells grown in IL-2." (PMID 28239463, 2017). "The fact that transgenic mice overexpressing IL-15 develop a neoplasm that mimics human CTCL reinforces the idea that IL-15 plays an important role in the disease pathogenesis." (PMID 27717961, 2017). "We observed that treatment with a reversible proteasome inhibitor bortezomib (1 mg/kg body weight) in tumor-bearing mice significantly enhanced the expression of lymphocyte-stimulatory cytokines IL-2, IL-12, and IL-15." (PMID 28052005, 2017). "We observed that IFNγ and granzyme-B expression on Vβ8.1/2+CD8+T cells in the spleens of tumor-bearing mice injected with IL-12 and IL-15 neutralization antibodies was significantly reduced compared with the expression in unneutralized tumor-bearing mice." (PMID 28052005, 2017). "Vγ2Vδ2 T cells expanded with IL-15 and pulse zoledronate stimulation showed identical tumor immunity upon in vivo testing to those expanded with IL-2." (PMID 28239463, 2017). "Tumor growth was significantly delayed in NOG-IL-2/IL-15 double Tg mice compared to NOG-IL-15 Tg mice." (PMID 29222435, 2017). "We also confirmed that IL-15 infusion increases the number of CD3–/NK1.1+ cells (NK cells) in the brains of tumor-implanted mice." (PMID 29286001, 2017). "Our data show that IL-15 has the potential to play an important role in the treatment of PDAC by stimulating NK cells to target both tumor cells and the surrounding desmoplastic barrier." (PMID 28915646, 2017). "In fact, PF in OC patients creates a complex and highly pro-tumor microenvironment with elevated levels of IL-6, IL-8, IL-10, IL-15, IP-10, MCP-1, MIP-1β, and VEGF." (PMID 28589429, 2017). "Human IL-12-, IL-15-, and IL-18-induced memory-like NK cells show higher expression of granzyme B and perforin and display enhanced cytotoxicity against K562 tumor cells." (PMID 28955340, 2017). "We used two highly metastatic tumor models to examine the anti-tumor efficacy of IL-15-SA/IL-15RαSu-Fc." (PMID 26910920, 2016). "From this perspective, IL-15 and these other adipocyte-derived factors appear to support tumor growth through both direct effects and also increased tumor vascularization." (PMID 27379019, 2016). "Culturing CD3/CD28-CAR-T in the presence of IL-7 and IL-15 gave the best effector activity while retaining a stem/memory against GD2 tumor antigen." (PMID 26999211, 2016). "In experimental models, it was shown that IL-15-expressing CD8+ T cells improve anti-tumor activity, and human IL-15 secreting cells perform also well in vivo." (PMID 27656185, 2016). "This more pronounced Th1 profile of γδ T cells, seen when IL-15 is present during expansion, also holds true upon addition of tumor cells to the cultures." (PMID 27686372, 2016). "This would implicate that IL-15 stimulation raises stronger cytotoxic γδ T cells, as effectively confirmed by the enhanced killing of tumor cells in our experiments." (PMID 27686372, 2016). "Here, the authors show that JAK pathway inhibition increases metastasis in mouse models of breast cancer by impairing NK anti-tumour activity and that these side effects can be overcome by addition of IL-15." (PMID 27406745, 2016). "On the 24th day after the i.p. administration with PLP/pIL15 or F-PLP/pIL15, IL15 expression in ascites and the serum of tumor bearing mice was determined by ELISA analysis." (PMID 27438147, 2016). "The potential of IL-15 to promote the survival and antitumor activity of adoptively transferred tumor-specific CD8+ T cells has been demonstrated in mice, but remains poorly understood in humans." (PMID 26824989, 2016).
tumor (continued). "NK cells from healthy donors upon activation with IL-2 and IL-15 kills indiscriminately both stem-like and differentiated tumor cells via stress ligand recognition." (PMID 27769244, 2016). "Pre-treatment of T cells with IL-7 and IL-15 or IL-15 and IL-21 was shown to increase T memory cell functions and anti-tumor activity of CAR-T cells." (PMID 26999211, 2016). "To identify immune strategies to restore CRC-NK functionality, we addressed different in vitro treatments, including the pre-incubation of tumor cells with cetuximab and NK cell stimulation with lenalidomide, IL-2, or IL-15." (PMID 27777574, 2016). "In that way, the IL-15-mediated effects are likely confined to the tumor environment, eluding systemic toxicity." (PMID 27656185, 2016). "The small number of studies performed to test the antitumoral activity of the recombinant murine IL-15 protein showed only marginal tumor effects." (PMID 27356750, 2016). "Accordingly, in the same model, Il15−/− mice showed more rapid tumor growth and died from lung metastases." (PMID 27148488, 2016). "The same trends were observed as prior to tumor cell exposure, i.e., a clear Th1 response for both IL-2 and IL-15-cultured γδ T cells." (PMID 27686372, 2016). "Among the various cytokines, the combination of CART cells and IL-15 or IL-21 administration mediated the best anti-tumor response, followed by IL-2 and IL-7, whereas IL-18 and only CART cells treated mice had the heaviest tumor burden." (PMID 27409425, 2016). "Preclinical ACT models, in which the effect of exogenous IL-7 and IL-15 on tumor outgrowth has been tested, demonstrated that both cytokines can improve tumor control, including in vaccinated lymphodepleted or immunodeficient hosts." (PMID 27656185, 2016). "It was also reported that pretreatment of isolated NK cells with IL-12, IL-15 and IL-18 resulted in increased antitumor activity, reduced tumor growth as well as cytokine-mediated induction of memory NK cells." (PMID 27821119, 2016). "Experiments in the B16 model has shown that mixing IL-21 with IL-15 improves expansion of transferred tumor-antigen-specific CD8+ T cells and enhances tumor control after vaccination." (PMID 27656185, 2016). "These IL15-conditions were sufficient to limit tumor formation in a lung metastasis model indicating that the NK cell populations were fully functional." (PMID 26822794, 2016). "Similar to the antigen-free conditions, IL-2-generated CART cells which were exposed to antigen-expressing tumor cells and IL-2, IL-7, or IL-15 showed enhanced expansion over other cytokines, with IL-15-exposed cells showing the least apoptosis." (PMID 27409425, 2016). "By harnessing NK cell effectors to eliminate tumor cells and presenting IL-15 locally in the immune synapse, we expect to achieve a better safety profile." (PMID 27650544, 2016). "CD56bright NK cells, when activated with cytokines such as IL-15, can become cytotoxic and even mediate lysis of target cells that are usually regarded as “NK-resistant”, such as the Daudi tumor cell line." (PMID 25951230, 2015). "Neutralizing IL-15 resulted in a statistically significant reduction of tumor-cell killing (p < 0.001), pointing to an important role for IL-15 in the observed killing effect." (PMID 26675759, 2015). "Cocultures of IL-15 EP DC and autologous NK cells resulted in an elevated killing of Daudi as compared to the basal level of NK cell-mediated tumor-cell killing (p < 0.001)." (PMID 26675759, 2015). "Most IL-15 TG mice were resistant to tumor formation (80% survival), whereas IL-15 KO mice proceeded to endpoint more quickly (n = 5/group)." (PMID 25879689, 2015). "Resting (unstimulated) NK cells already displayed considerable cytotoxicity towards the K562 tumor cell line, but this activity was nevertheless significantly enhanced by IL-15 DCs (P<0.001)." (PMID 25951230, 2015).
tumor (continued). "Adenovirus armed with RANTES and IL-15 has also been used in vivo to enhance the infiltration of tumour-directed chimeric antigen receptor (CAR)-T cells, used in adoptive T cell therapy." (PMID 26633468, 2015). "CXCL9 was also induced in the metronomic CPA-treated tumor cells in association with other extracellular immune activators: TNFSF4, MICB, interleukins IL12, IL15, IL23, and IL17RB, and interferon response genes." (PMID 25952672, 2015). "As an example, a DNA vaccine encoding for IL-21 and IL-15 genes linked to the 47-LDA mimotope of disialoganglioside GD2, an antigen expressed mainly in NB, was particularly effective in inhibiting tumor growth in mice bearing NXS2 GD2+ NB." (PMID 25961061, 2015). "We describe that IL-15 increases NK1.1+ and CD69+ cell infiltration in tumour area and that NK cell depletion reduces the efficacy of IL-15 administration on tumour growth and of EE on tumour growth and mice survival." (PMID 25818172, 2015). "Although IL-15/IL-15Rα EP DC are promising candidates for DC-based vaccination in cancer immunotherapy, the tumor suppressive environment can impede its powerful antitumor effects." (PMID 26675759, 2015). "We demonstrate that brain infusion of IL-15 increases the frequency of NK cell infiltrating the tumour and that NK cell depletion reduces the efficacy of EE and IL-15 on tumour size and of EE on mice survival." (PMID 25818172, 2015). "Its significance is further highlighted by clinical trials in which IL-15 is being used to boost the proliferation and anti-tumor response of NK cells." (PMID 26257729, 2015). "This environment–brain–tumour connection appears to be mediated by IL-15 and BDNF, cytokines whose level increases in the brain of EE-housed mice." (PMID 25818172, 2015). "In contrast IL-15 KO/MT mice had faster tumor formation and decreased survival when compared to MT or IL-15 TG/MT mice." (PMID 25879689, 2015). "Recently, the clinical interest of using IL-15 was further strengthened because IL-2 administration also expanded regulatory T cells, which suppress the anti-tumor response of NK cells and effector T cells." (PMID 26257729, 2015). "Phenotyping the CD8 T cells from these mouse strains revealed a large proportion of IL-15 TG/MT tumor CD8 T cells that also expressed NK1.1." (PMID 25879689, 2015). "Blocking IL-15 transpresentation abrogated NK cell-mediated cytotoxicity against tumor cells, pointing to a pivotal role of IL-15 transpresentation by IL-15Rα to exert its NK cell-activating effects." (PMID 26675759, 2015). "Lastly, the tumors that formed in IL-15 TG/MT CD8 depleted mice had similar tumor destruction to that seen in normal IL-15 TG/MT mice." (PMID 25879689, 2015). "Previously it was shown that DC-derived IL-15 is able to stimulate proliferation and activation of these immune effector cells in both a virus- and tumor-related setting." (PMID 26675759, 2015). "In contrast, IL-15 TG/MT tumors were mainly necrotic with very few healthy tumor cells, had increased lymphocytic infiltration and TUNEL stain revealed cell death throughout." (PMID 25879689, 2015). "We show that IL-15 infusion in tumour-bearing SE mice has the same effect of EE both on tumour size and on NK cell accumulation in the tumour area, confirming its potential antiglioma activity." (PMID 25818172, 2015). "Direct administration of IL-15 has shown antitumor effects in several preclinical mouse tumor models." (PMID 25997501, 2015). "To further examine the impact of CD8 T cells from IL-15 TG/MT mice on tumor formation, we performed CD8 T cell adoptive transfers." (PMID 25879689, 2015). "Our observations corroborate these findings, including enhanced killing of tumor cells if IL-15 is presented by IL-15Rα, as seen by us using healthy donor and cancer patient material." (PMID 26675759, 2015). "Both IL-15 and IL-21 have been shown in multiple experiments to enhance the in vivo anti-tumor effects of CD8+ T cells and in some cases to potentiate tumor regression." (PMID 25903148, 2015).